NKD1 (NKD inhibitor of Wnt signaling pathway 1)
Diseases named in the same sentence as NKD1 in open-access papers (continued):
Sharing a sentence is not in itself a finding about the gene and the disease.
pancreatic ductal adenocarcinoma (1 paper, 2018). An infiltrating adenocarcinoma that arises from the epithelial cells of the pancreas. "Knockout of FZD5 robustly inhibited cell growth in human Ring finger protein 43 (RNF43)-mutant pancreatic ductal adenocarcinoma cells (PDAC) in clonogenic growth assays, and editing of FZD5 significantly inhibited the expression of WNT target genes AXIN2 and NKD1(Naked cuticle homolog 1)." (PMID 29789460, 2018).
Right ventricular hypertrophy (1 paper, 2023). In this case the right ventricle is more muscular than normal, causing a characteristic boot-shaped (coeur-en-sabot) appearance as seen on anterior- posterior chest x-rays. "Upregulating NKD1 by Ad-Nkd1 transfection attenuated the increase in right ventricular systolic pressure (RVSP), right ventricular hypertrophy index (RVHI), pulmonary vascular wall thickening, and vascular β-catenin expression after MCT treatment." (PMID 37857014, 2023). "Ad-Nkd1 transfection attenuated the increase in right ventricular systolic pressure (RVSP), right ventricular hypertrophy index (RVHI), and vascular β-catenin expression after MCT treatment, as well as pulmonary vascular wall thickening." (PMID 37857014, 2023).
serous ovarian cancer (1 paper, 2023). "Similarly, a later study defined NKD1 methylation as an important unfavorable prognostic factor for a risk model of high-grade serous ovarian cancer." (PMID 36969985, 2023).
tooth agenesis (1 paper, 2026). A tooth disease characterized by failure to develop one or more missing teeth. "Given that impaired nuclear translocation of MSX1 is a known cause of tooth agenesis, we hypothesized that NKD1-mediated nuclear translocation of MSX1 might be a critical mechanism driving progenitor cell differentiation into odontoblasts." (PMID 41526338, 2026).
tumor (34 papers, 2008 to 2026). "Given the genetically independent nature of MM tumours and the low likelihood of the same gene being mutated at different positions in more than one sample, the presence of different mutations in Nkd1 in two BALB/c samples and Cacna2d2 in samples from two different strains is informative." (PMID 28577549, 2017). "Abnormal expression of NKD1 is correlated with HCC tumor intra- or extra-hepatic metastasis, which implies that NKD1 might be associated with HCC cell invasion and metastatic ability." (PMID 27231134, 2016). "Since MSI tumors are prone to mutation throughout the genome, the question arises of whether the NKD1 mutations drive tumor progression or are merely “bystander” mutations." (PMID 19956716, 2009). "We removed and photographed the subcutaneous tumors from nude mice and found that knocking out the NKD1 gene resulted in a significant reduction in tumor volume, whereas overexpression of MYC in SW620-nkd1−/− cells markedly increased the tumor volume." (PMID 40675969, 2025). "Among the top 100 deregulated genes, Wnt-associated genes such as LGR5, DKK1, and NKD1, as well as the HB-related genes DUSP9, DLK1, PEG3, PEG10, IGF2BP1, and IGF2BP2 were consistently upregulated in tumor samples." (PMID 40968384, 2025). "NKD1 was strongly expressed in the cholangiocyte-like population or hybrid tumor cell with biliary and hepatocyte marker genes as well as the cycling hepatocytes." (PMID 40766612, 2025). "These cells also expressed general WNT target genes, such as NOTUM and NKD1, but at a lower level than the embryonal tumor cluster." (PMID 39567475, 2024). "Since clinical evidence implied a potential tumor-suppressing role of NKD1, we next conducted cellular experiments to validate its detailed effects in GBM." (PMID 36969985, 2023). "The regulation of NKD1 on tumor progression is biphasic, resulting from the biphasic modulatory effects of NKD1 on proliferation and migration of different tumor cells." (PMID 37857014, 2023). "Both the colony formation assay and MTT proliferation assay revealed an attenuated GBM growth after overexpressing NKD1, highlighting the crucial role of NKD1 as a novel tumor suppressor." (PMID 36969985, 2023). "As a negative regulator of Wnt/β-catenin pathway, naked cuticle homolog 1 (NKD1) is originally involved in the tumor growth and metastasis via affecting the proliferation and migration of different types of cancer cells." (PMID 37857014, 2023). "Since dysregulation of NKD1 has been observed in many types of neoplasms, the regulatory roles of NKD1 in cancer are receiving widespread attention." (PMID 37857014, 2023). "Since the expression of NKD1 is dysregulated in a series of cancers, NKD1 is considered as an important regulator or predictor of tumor progression." (PMID 37857014, 2023). "The expression of classical CTNNB1‐dependent transcriptional Wnt targets such as AXIN2 and NKD1 was elevated in a large fraction of tumor samples compared with normal tissue." (PMID 35904277, 2022). "Len-sh-circ_PVT1 promotedhe texpression of DKK1, NKD1, and p-GSK3β and inhibited wnt4 and β-catenin in tumor." (PMID 34336825, 2021). "Consistently, ectopic expression of NKD1 significant decreased Rac1 protein level in transplanted tumor tissue." (PMID 27231134, 2016). "The NKD1 protein is abnormally expressed in many neoplasms and plays an important role in tumor progression." (PMID 27231134, 2016). "Furthermore, NKD1 was elevated in specific mouse models of intestinal tumors comparing to healthy tissues, which represents a biomarker of tumor growth." (PMID 36969985, 2023). "We performed qPCR on a subset of genes that were either among the most significant DEGs identified in our analysis of colon organoids of FAP versus healthy subjects and/or were significant in an analysis of either EOCRC tumor datasets: NKD1, EYA2, EGR2, EPDR1 and IGFL1." (PMID 36077675, 2022).
tumor (continued). "Strikingly, they found that ligand-dependent tumours tend to silence genes encoding Wnt antagonists, such as AXIN2, NKD1, APCDD1, NOTUM, and DKK4, whereas ligand-independent tumours effectively bypass Wnt-pathway negative feedback loops without the need for such selective pressure." (PMID 33673710, 2021). "We also found components of the β-catenin destruction complex, namely Axin1 itself and its key binding partner, the APC tumour suppressor, as well as AMER1 and β-catenin, suggesting that the entire complex is associated with Nkd1 HisC aggregates in Wnt-stimulated cells." (PMID 33025907, 2020). "NKD1 is involved in Wnt signaling central to tumor cell growth in CRC and other cancers." (PMID 30704450, 2019). "Several of the genes upregulated in CTNNB1-mutated tumours have previously been described as overexpressed in CTNNB1-mutated adrenal lesions, regardless of type of hormone production or differentiation level: AFF3, ISM1, NKD1, ENC1 and RALBP131,32." (PMID 31000732, 2019). "Indeed, several genes such as CTNNB1, CCND1 and NKD1 involved in the Wnt/β-catenin signaling pathway showed increased m6A methylation in tumor tissues with respect to normal." (PMID 31870368, 2019). "Given that above data suggested that NKD1 may be a target of miR-744 in PCa cells, we decided to investigate the relationship between NKD1 and miR-744 in PCa tumor samples." (PMID 28107193, 2017). "Above results, together with several pieces of evidence that NKD1 is a well-known negative regulator of Wnt signaling in a variety of tumor types, we therefore hypotheses that NKD1 is a main direct regulators of miR-744." (PMID 28107193, 2017). "Dysregulation of NKD1 has been reported in many types of neoplasms." (PMID 27231134, 2016). "This raises a question of whether the expression level of NKD1 protein is parallel to the mRNA level in the same tumor type." (PMID 21599923, 2011). "Taken together, our data support the hypothesis that the specific alteration of Nkd1's ability to promote Dvl turnover might activate Wnt/β-catenin signaling during CRC tumor progression." (PMID 19956716, 2009). "Therefore, NKD1 shows distinct expression patterns in different tumor types." (PMID 36969985, 2023). "High tumor-intrinsic expression of NOTUM, NKD1, and SERPINA3, together with elevated CD8+ T cell infiltration and a reduced Treg/CD3+ ratio within the TME, robustly associated with major pathological response (MPR)." (PMID 42220510, 2026). "The embryonal HBTOs were enriched with WNT target genes and EMT markers, including AXIN2, LEF1, DKK1, NOTUM, NKD1 and VIM, in line with the embryonal tumor signature." (PMID 39567475, 2024). "The genes most differentially expressed in the analysis of cell lines were the same genes as the ones with strong expression differences between Wnt‐high and Wnt‐low tumor samples, namely GNAI1, NKD1, and TCF7." (PMID 35904277, 2022). "Key Wnt negative regulator genes were differentially expressed between LD/LI tumours, with targeted hypermethylation of some genes (AXIN2, NKD1) occurring even in CIMP-negative LD cancers." (PMID 31563876, 2020). "Analysis of leading-edge genes within the NR signature identified five consensus differentially expressed NRs in the two discovery cohorts, all expressed at a significantly higher level in LI versus LD tumours—AXIN2, NKD1, APCDD1, NOTUM and DKK4." (PMID 31563876, 2020). "Our previous study showed that NKD1 protein is down regulated in HCC tissues and correlated with poor differentiation, tumor size, and intra- or extra-hepatic metastasis." (PMID 27231134, 2016). "However, preventing direct Nkd1/Dvl association is apparently insufficient to promote neoplasia, as deletion of the Dvl-binding Nkd1 EFX motif neither rendered mutant mice susceptible to cancer nor potentiated the frequency of Apc mutation-driven intestinal adenomas." (PMID 19956716, 2009).
tumor (continued). "The correlation between NKD1, FZD3 and FZD6 and β-catenin stabilisation indicates a cell autonomous effect in the tumour epithelium." (PMID 18414471, 2008). "For example, Wnt2, Wnt7, and disheveled segment polarity protein 3 (DVL‐3) are upregulated in tumors, while negative regulators like naked cuticle homolog 1 (NKD1) and NKD2 are significantly downregulated, underscoring the crucial role of the Wnt pathway in HBV‐related tumor development." (PMID 40060195, 2025). "In addition to regions exhibiting fetal tumor characteristics, we also identified areas with embryonal tumor features in this tissue, characterized by high levels of WNT target genes such as NOTUM, DKK1/4, NKD1, APCDD1." (PMID 39567475, 2024). "Moreover, to the best of our knowledge, the relationship between NKD1 expression and clinicopathological features in human tumor has not been reported in the English literature." (PMID 21599923, 2011). "However, it is currently unclear whether or not NKD1 protein expression is in parallel to the mRNA expression in the same individual tumor." (PMID 21599923, 2011).
cancer (22 papers, 2008 to 2026). A tumor composed of atypical neoplastic, often pleomorphic cells that invade other tissues. "We report three cancer-associated human NKD1 mutations that alter Wnt/β-catenin signaling and disrupt Nkd1/Dvl binding." (PMID 19956716, 2009). "As a negative regulator of Wnt signaling, NKD1 suppresses proliferation in several cancer cell types via reducing β-catenin expression." (PMID 37857014, 2023). "Previous studies demonstrate that NKD1 can inhibit proliferation and migration in several cancer cell lines via inhibiting β-catenin." (PMID 37857014, 2023). "Survival analysis revealed that patients with low NKD1 protein levels in GBM samples exhibited significantly worse cancer-specific survival than those with high-NKD1 protein levels (P = 0.027)." (PMID 36969985, 2023). "The modulatory role of NKD1 in cancers largely rely on its regulation of cellular proliferation and migration." (PMID 37857014, 2023). "Taken together, inhibition of NKD1 expression significantly suppressed cancer cell proliferation both in vitro and in vivo." (PMID 34547189, 2021). "Among the roles previously demonstrated for H19 as a modulator of cancer cells, one mechanism of action in the nuclear compartment involves the epigenetic modulation of the expression of Nkd1, an inhibitor of Wnt pathway." (PMID 29643989, 2018). "Although there are increasing reports of NKD1 today, the role of NKD1 in cancer progression still needs to be further addressed." (PMID 21599923, 2011). "Future experiments will focus on understanding how the mutant Nkd1 proteins alter Wnt signaling during cancer progression in vivo." (PMID 19956716, 2009). "Levels of MFNG in this subgroup of tumors also determined the transcriptional status of several Notch target genes such as NKD1, DLX3, EREG, EPHA4, or IL7R, known to be relevant for cancer progression." (PMID 30065304, 2018). "Some of them are cancer related, such as POU2F3, NKD1 and CYP2C8, while LINC00189, GCC2 and OR9Q1 genes are rarely reported in human diseases." (PMID 27602771, 2016). "Given the crucial roles for Dsh/Dvls in “non-canonical” Wnt pathways that govern planar-cell-polarity and cell migration in vertebrates, the NKD1 mutations might also alter Dvl activity in non-canonical Wnt pathways that control cell polarity or migration during cancer progression." (PMID 19956716, 2009). "Among the cancer-specific states, we identified a stem-like state absent in the healthy colon, characterized by upregulation of WNT antagonists, including NOTUM, NKD1, and APCDD1." (PMID 40393458, 2025).
infection (1 paper, 2022). The state of being infected such as from the introduction of a foreign agent such as serum, vaccine, antigenic substance or organism. "On the other hand, the de-regulators of the Wnt pathway, namely, Naked-1 (Nkd-1) and phosphorylated Axin (pAxin) were reciprocally expressed to Wnt and LRP6 phosphorylation after 12 h of infection." (PMID 35336965, 2022).
NKD1 also shares sentences with these, for which no sentence is quoted: hepatoblastoma (3 papers); osteosarcoma (3); acute myeloid leukemia (2); pancreatic cancer (2); rectal cancer (2); adenocarcinoma (1); adrenal tumours (1); Cirrhosis (1); colorectal (1); diabetes (1); esophageal cancer (1); Hypertension (1); intestinal tumors (1); lung adenocarcinoma (1); Lymphatic Metastasis (1); male infertility (1); medulloblastoma (1); Obesity (1); oligoastrocytoma (1); oligodendroglioma (1); pulmonary arterial hypertension (1); renal fibrosis (1); squamous carcinoma (1); squamous cell carcinoma of urinary bladder (1); Strabismus (1); thyroid cancer (1).